SPARC (secreted protein acidic and cysteine rich)
Diseases named in the same sentence as SPARC in open-access papers (continued):
Sharing a sentence is not in itself a finding about the gene and the disease.
colorectal cancer (52 papers, 2003 to 2025). A primary or metastatic malignant neoplasm that affects the colon or rectum. "For example, depletion of USP22 induced upregulation of secreted protein acidic and rich in cysteine (SPARC) by affecting H3K27ac and H2Bub1 occupancy on the SPARC gene in inflammation-associated colorectal cancer." (PMID 35965507, 2022). "On the other hand, SPARC expression was also associated with good prognosis of neuroblastoma, ovarian, and colorectal cancer." (PMID 35670884, 2022). "In colorectal cancer, where obesity is also a well-known risk factor, stromal SPARC underexpression in IHC is associated with poor overall survival and poor progression free survival." (PMID 28505082, 2017). "We previously showed that lower levels of SPARC were associated with therapy-refractory colorectal cancers (CRC), and that upregulating its expression enhances chemo-sensitivity resulting in greater tumour regression in vivo." (PMID 18458674, 2008). "We previously showed that SPARC gene and protein expression was decreased in colorectal cancers and that lower levels were associated with reduced sensitivity to chemotherapy." (PMID 18458674, 2008). "Increased levels of SPARC were associated with lymph node metastasis in colorectal and oesophageal cancers, liver metastasis in colorectal cancer and bone metastasis in prostate cancers." (PMID 15558074, 2004). "Thus, we demonstrated high prognostic significance of angiogenesis-associated factors S100A4, SPP1 and SPARC that are produced by TAMs in colorectal cancer." (PMID 36895491, 2023). "Hsa_circ_0004104, also referred to as circRNA SPARC, is upregulated in colorectal cancer and promotes cancer cell migration and proliferation through the JAK/STAT pathway." (PMID 40626007, 2025). "In the realm of colorectal cancer, SPARC enhances the chemosensitivity of resistant cells either paired with chemotherapy agents or combined with vitamin D." (PMID 38650694, 2024). "Expression levels of the SPARC gene are notably correlated with clinical attributes of colorectal cancer, such as tumor stage, suggesting its potential as a biomarker for colorectal cancer." (PMID 39336798, 2024). "Consistently, exogenous SPARC administration has demonstrated a suppression of growth in a spectrum of cancers including pancreatic cancer, colorectal cancer, neuroblastomas, and leukemia." (PMID 38650694, 2024). "In a study using a murine azoxymethan-induced colorectal cancer model with SPARC-knockout, low-intensity treadmill exercise three times each week for 6 weeks markedly suppressed aberrant crypt focus formation in wild-type mice." (PMID 37554940, 2023). "SPARC has been found to be released from skeletal muscle into circulation after a single period of exercise in healthy humans and in rats with colorectal cancer." (PMID 37958310, 2023). "As a myokine, SPARC has the potential to contribute to the preventive effects of exercise on colorectal cancer by inducing apoptosis." (PMID 37554940, 2023). "The group with the higher SPARC level was younger, taller, and heavier, and had less esophageal cancer, more colorectal cancer, and more adenocarcinoma than the group with lower SPARC levels." (PMID 32512862, 2020). "It has been suggested that SPARC is a tumor suppressor, as changes in SPARC expression affect sensitivity to radiation and chemotherapy in patients with colorectal cancer." (PMID 33019579, 2020). "Further knockdown experiments using colorectal cancer cells revealed invasion or migration promoting roles for SPARC, FN1 and FSCN1." (PMID 30473751, 2018). "In this study, we found that hsa-miR-29c-3p inhibited the biological function of colorectal cancer cells by targeting SPARC." (PMID 29262657, 2017). "On the other hand, in colorectal cancer, SPARC was suggested to have a pro-tumorigenic and pro-metastatic function." (PMID 27421134, 2016).
colorectal cancer (continued). "In colorectal cancer cell lines, overexpression of SPARC reduced cell viability and enhanced apoptosis in cells exposed to various chemotherapeutic agents." (PMID 20525171, 2010). "This change in SPARC expression in tumorigenesis and its role in promoting chemotherapy sensitivity led us to investigate the potential mechanisms involved in repressing SPARC in colorectal cancers." (PMID 18458674, 2008). "In this study, we found an overall methylation pattern of 60% in the SPARC promoter of primary colorectal cancer specimens, while only 28% of the CpG sites were partially methylated." (PMID 18458674, 2008). "Overall, a significantly higher proportion of CpG sites were methylated within the SPARC promoter in colorectal cancers (60%), while only 35% of the sites were methylated in normal colon (P=0.03)." (PMID 18458674, 2008). "Among these, ZEB1, SPARC, CDH1 and EpCAM were the most significantly differentially expressed genes between TRPS1-WT and TRPS1-MT cells and had been previously associated with colorectal cancer metastasis." (PMID 39307879, 2024). "For instance, IL-6 in liver cancer and SPARC in colorectal cancer have been found to be affected." (PMID 37510502, 2023). "Low expression of SPARC is an independent unfavorable prognostic factor of colorectal cancer." (PMID 30175151, 2018). "SPARC expression is an unfavorable outcome in gastric, prostate and lung cancers, while as a favorable prognostic indicator, SPARC has been reported for colorectal cancer." (PMID 26731428, 2016). "In colorectal cancer, SPARC expression in MSC (HR, 0.654; CI,0.409–1.048; p = 0.028; HR, 0.536; CI, 0.359–0.802; p = 0.002) were all independent prognostic factors for OS and DFS, respectively, and the low expression of SPARC was also related with the high level of TNM." (PMID 26731428, 2016). "Furthermore, Sp1 and Elk-1 bind to the caspase-8 promoter and induce apoptosis in colorectal cancer cells in response to SPARC treatment." (PMID 25693514, 2015). "Additionally, the up-regulated expression of SPARC was shown to improve effectiveness of radiotherapy and chemotherapy in colorectal cancers." (PMID 20687958, 2010). "In others, mainly ovarian, neuroblastomas, and colorectal cancers, SPARC may function as a tumour suppressor." (PMID 19920824, 2010). "This hypothesis will require a prospective study to determine if partial or complete methylation of the SPARC promoter in the ‘normal’ colon can be predictive of future development of colonic polyps and later, colorectal cancers." (PMID 18458674, 2008). "Recent studies using genome-wide screening to identify genes that are targeted for aberrant methylation in tumours have also consistently shown SPARC expression to be inducible by 5-Aza-2′deoxycytidine, in pancreatic, cervical, and colorectal cancer cell lines." (PMID 18458674, 2008). "In colorectal cancer, SPARC (Secreted Protein, Acidic and Rich in Cysteine) interference ERS to further enhance apoptosis by regulating the UPR; the low expression of SPARC and GRP78 prompts settlement colorectal cancer patients with a lower survival rate." (PMID 32850882, 2020). "In colorectal cancer (CRC), SPARC can function as a sensitizer to conventional chemotherapy by enhancing apoptosis by interfering with the activity of Bcl-2." (PMID 31243264, 2019). "In addition, in response to secreted protein, acidic and rich in cysteine (SPARC) expression, Sp1 and Elk-1 bind to the caspase-8 promoter and induce apoptosis in MIP101 colorectal cancer cells." (PMID 25693514, 2015).
prostate carcinoma (47 papers, 2003 to 2025). A carcinoma that arises from epithelial cells of the prostate gland. "Conflicting reports have described the expression levels of SPARC to be either increased or decreased in association with advanced prostate cancer." (PMID 25331979, 2014). "We also tested the effect of SPARC on the invasive potential of other prostate cancer cells, finding that recombinant human SPARC caused an enhanced invasiveness of the androgen-independent Du-145 and 22Rv1 cells, but not the androgen-dependent LNCaP cells." (PMID 25331979, 2014). "Furthermore, SPARC, a matrix-associated protein expressed and secreted by prostate cancer cells, induces dormancy of bone cells, a process sustained by SPARC-mediated activation of BMP7 secretion." (PMID 34135460, 2021). "In support to our suggestion, increased SPARC levels have been shown to increase the production and activity of MMPs, leading to matrix degradation in breast and prostate cancers." (PMID 38347494, 2024). "Prostate cancer cells are known to secrete a high level of SPARC protein when they are in the dormant stage of early bone metastasis." (PMID 36552843, 2022). "SPARC is expressed during extracellular matrix remodeling and is abundant in bone marrow and high-grade prostate cancer (PCa)." (PMID 35682554, 2022). "Dark contrast was detected only in the SPARC-expressing prostate cancer, demonstrating that M13-SBP-MNP is able to specifically target prostate cancer." (PMID 36714624, 2022). "This idea is supported by two studies, reporting that BMP7 and SPARC, respectively, maintain prostate cancer cells in dormancy by inducing senescence." (PMID 34135460, 2021). "To date, only one study on cath-K in prostate cancer 61 validated in vitro, in cellulo and in vivo SPARC cleavage events by proteases in cancer." (PMID 33995652, 2021). "Both SPARC and Fetuin-A antibodies were detected in the sera, with significantly lower levels in both CA and AA prostate cancer patients compared to healthy controls." (PMID 33672007, 2021). "The range of auto-antibodies reactivity to SPARC and Fetuin-A was similar in both CA and AA prostate cancer patients, indicating a similar behavior also across ethnic groups." (PMID 33672007, 2021). "A previous study has shown that a conditioned medium of SPARC treated bone marrow stromal cell can activate p38-MAPK signaling in prostate cancer." (PMID 31548362, 2019). "Similar to our results, the close association between SPARC expression and worse differentiation was previously observed in ovarian and prostate cancer, and was supposed to be due to the modulation of SPARC on the cell-matrix interactions." (PMID 28053291, 2016). "SPARC expression levels were extremely low or undetectable in the androgen-independent Du-145 and CWR22Rv1 (henceforth, 22Rv1) prostate cancer cells and in the androgen-dependent LNCaP cells." (PMID 25331979, 2014). "Based on our observations, we conclude that neoplastic-produced SPARC constitutes a potential tumor progression biomarker and a therapeutic target in advanced prostate cancer." (PMID 25331979, 2014). "In most primary human prostate cancer samples, SPARC was expressed in the epithelial tumoral compartment of metastatic cases." (PMID 25331979, 2014). "Upregulation of VEGF production by SPARC provides metastatic prostate cancer cells with a specific growth advantage in the bone microenvironment, thus blocking the interaction of SPARC with activated αv integrins should reduce bone metastasis." (PMID 24213501, 2012). "Four candidates (Decorin, SPARC, Spry-1, Tsukushi) were immunolocalised in human foetal prostate (weeks 14, 16, 19) and expression of Decorin was evaluated on a human prostate cancer tissue microarray." (PMID 22880013, 2012). "αvβ3 and αvβ5 mediate the preferential migration of metastatic prostate cancer cells to bone-derived secreted protein acidic and rich in cysteine (SPARC)." (PMID 24213501, 2012).
prostate carcinoma (continued). "Previous studies using prostate cancer tissue samples reported that SPARC expression was higher in metastatic sites than in the primary site." (PMID 22321704, 2012). "On the other hand, downregulation of endogenous SPARC by small interference RNA accelerates prostate cancer cell-line proliferation and matrix invasiveness." (PMID 21206493, 2011). "Especially, SPARC has been assumed to be important in human prostate cancer bone metastasis as a major bone-derived chemoattractant for prostate cancer cells." (PMID 21206493, 2011). "In addition, when lung carcinoma, T-lymphoma cells, or prostate cancer cells were subcutaneously injected in SPARC knockout mice, tumor growth was enhanced." (PMID 38928185, 2024). "Similarly, cathepsin K cleaves SPARC in vitro and in vivo in its N‐terminal acid domain and in its extracellular Ca2+ binding domain in mice harboring prostate cancer bone metastases." (PMID 36346290, 2023). "In vitro, SPARC increases breast and prostate cancer cells migration and invasion." (PMID 28505082, 2017). "However, SPARC is also reported to play a different role in breast and prostate cancers, with a tumor suppressive function." (PMID 28969021, 2017). "In contrast, reducing stromal cell-secreted SPARC increased Akt phosphorylation in prostate cancer." (PMID 28969021, 2017). "In addition, exogenous SPARC stimulation results in reducing phosphorylation of AKT in prostate cancer cells." (PMID 28718842, 2017). "For example, in prostate cancer, SPARC may function as a tumor suppressor since down-regulation or inactivation of SPARC enhances aggressive and metastatic behavior." (PMID 27421134, 2016). "Taken together, these results indicate that SPARC is the major factor responsible for the enhanced invasiveness of M cells stimulated by S-CM, and that it can stimulate the invasiveness of other androgen-independent prostate cancer cells." (PMID 25331979, 2014). "The observed staining for SPARC in the epithelial tumoral component of prostate cancer samples could be attributed either to endogenous SPARC produced by tumor cells, or to stromally produced SPARC uptaken by neoplastic cells." (PMID 25331979, 2014). "SPARC is expressed in the neoplastic cells of primary prostate cancer samples from metastatic cases, and could thus constitute a tumor progression biomarker and a therapeutic target in advanced prostate cancer." (PMID 25331979, 2014). "Thus, SPARC expression is elevated in many tumor types, including prostate cancer, and it has been found to enhance the migration and invasiveness of prostate cancer cells." (PMID 25331979, 2014). "We thus performed an immunohistochemical analysis of SPARC expression in primary prostate carcinoma samples associated, or not, with lymph node involvement (metastatic or non-metastatic primary tumors, respectively)." (PMID 25331979, 2014). "We have found that both primary prostate cancer samples associated with metastasis and those without metastatic association express SPARC in their stromal components at variable levels that do not correlate with metastatic status." (PMID 25331979, 2014). "However, the increased SPARC expression in prostate cancer, bladder cancer and non-small cell lung cancer indicated a higher malignancy and invasion of tumors with poor prognosis." (PMID 20565704, 2010). "Moreover, it has been reported that SPARC promotes cell migration and invasion in prostate cancer and glioblastoma." (PMID 14562024, 2003). "SPARC is expressed in primary prostate cancer cells and metastatic samples, and thus could be a tumor progression biomarker and a therapeutic target in advanced prostate cancer." (PMID 37509139, 2023). "Hence, reinstating SPARC expression in bone DTCs by treatment with either 5-AZA or with COX2 inhibitor NS398 may offer a therapeutic window to treat recurrent prostate cancer disease." (PMID 33987095, 2021).
prostate carcinoma (continued). "SPARC was shown to be epigenetically silenced in aggressive cells by promoter methylation whereas treatment of prostate cancer cells with the DNA demethylating agent 5-azacytidine (5-AZA) or with the COX2 inhibitor NS398 could restore SPARC expression in malignant prostate cancer cells." (PMID 33987095, 2021). "selected epigenetically altered genes in prostate cancer and found AR, GSTP1, RARB, SPARC, TIMP3, and NKX2-5 to be hypermethylated in AA patients." (PMID 36937425, 2023). "Secreted protein acidic and rich in cysteine (SPARC)-binding peptide (SBP; a prostate cancer-specific peptide) and magnetic iron oxide particles were attached to the p3 and p8 capsid proteins, respectively (M13-SBP-magnetic nanoparticles (MNPs))." (PMID 36714624, 2022). "These proteins include MMP-9, which can be used as a biomarker for cancer; SPARC, an acidic secretory protein rich in cysteine, was positively correlated with CTSK expression and predicted a poor prognosis in prostate cancer and gastric adenocarcinoma." (PMID 36005209, 2022). "Similarly, the cysteine cathepsin K (cath-K) also cleaves SPARC in vitro and in vivo in its N-terminal acid domain, and in its extracellular Ca2+ binding domain in prostate cancer bone metastases, releasing a 10-kDa C-terminal fragment with unknown biological activity." (PMID 33995652, 2021). "The expression of SPARC and DCN is significantly higher in prostate cancer cell lines that actively invade the astrocyte monolayer." (PMID 34503278, 2021). "Recently, indolent prostate cancer cells have been reported to secrete SPARC, which can induce BMP7 secretion by bone marrow stromal cells, further supporting the role of BMP7 in inducing prostate cancer stem cell senescence." (PMID 27782035, 2016). "Past reports have shown that, when prostate cancer patients perform regular supervised exercise, blood levels of myokines such as secreted protein acidic and rich in cysteine (SPARC) and OSM are elevated compared to those in the no-exercise group." (PMID 38539521, 2024). "Regarding human prostate cancer, a very interesting study showed that Apigenin was able to suppress EMT either in vitro or in vivo in a dose and time-dependent manner by targeting SPARC/osteonectin, cwcv, and kazal-like domains proteoglycan 1 (SPOCK1)-snail/slug axis." (PMID 38791608, 2024). "Moreover, we found that both SPARC and COL1A1 harbor SNVs and CNVs in TCGA prostate cancer samples and their expressions were obviously correlated to the survival of patients." (PMID 34131148, 2021). "SPARC (osteonectin), cwcv and kazal-like domains proteoglycan 2 (SPOCK2) is known as a secreted protein that is acidic and cysteine-rich, playing a significant role in the development and progression of ovarian cancer, endometrial cancer, and prostate cancer." (PMID 33244319, 2020). "The matricellular protein SPARC, secreted by a prostate cancer clonal tumor cell subpopulation displaying non-CSC properties, is a critical mediator of paracrine effects exerted on a distinct tumor cell subpopulation enriched in CSC." (PMID 25331979, 2014). "SPARC levels were determined by immunohistochemistry and real-time RT-PCR in tumors and by ELISA in plasma from patients with metastatic or non-metastatic prostate cancer." (PMID 25331979, 2014). "We found that plasma SPARC levels in metastatic prostate cancer patients tended to be lower than those in non-metastatic cases or control individuals, and thus we conclude that plasma levels of SPARC in prostate cancer patients do not reflect tumoral SPARC expression levels." (PMID 25331979, 2014). "As a matricellular protein SPARC, secreted by a clonal tumor cell subpopulation displaying non-cancer stem cell (CSC) properties in prostate cancer, is a paracrine factor exerted on a distinct tumor cell subpopulation enriched in CSCs." (PMID 37509139, 2023).
prostate carcinoma (continued). "Here we report that the matricellular protein SPARC is the major diffusible factor produced by the PC-3S non-CSC clonal subpopulation that mediates the enhanced invasiveness and metastatic dissemination of the CSC-rich PC-3M subpopulation of the PC-3 prostate cancer cell line." (PMID 25331979, 2014).